IL25 (interleukin 25)
Diseases named in the same sentence as IL25 in open-access papers (continued):
Sharing a sentence is not in itself a finding about the gene and the disease.
eosinophilia (continued). "In the present study, we clearly demonstrated that airway eosinophilia was significantly reduced in EC sensitized IL-25-/- mice and EC sensitized IL-33-/- mice compared with EC sensitized WT mice, indicating that both IL-25 and IL-33 are crucial for development of airway inflammation in the setting." (PMID 26230091, 2015). "Administering IL-25 peritoneally has been shown to induce IgE isotype switching and eosinophilia." (PMID 22539101, 2012). "Additionally, researchers have discovered that IL-25 maintained intestinal barrier integrity during CDI by inducing the increase of eosinophilia, and restoring the suppressed expression of IL-25 in CDI could decrease mortality and morbidity." (PMID 41158525, 2025). "Succinate stimulates interleukin 25 (IL25) production through this receptor, thereby inducing a type 2 immune response, which is associated with the activation of type 2 naïve lymphoid cells (ILC2), eosinophilia, and increased TC and goblet cell differentiation." (PMID 38892399, 2024). "Therefore, we examined whether TSLP, IL-25 and/or IL-33 contribute to induction of eosinophilia in the BAL fluid of mice after inhalation of large-size chitin (70–100 μm)." (PMID 33723298, 2021). "Alarmins such as thymic stromal lymphopoietin (TSLP), IL-25 (IL-17E), and IL-33 stimulate type 2 ILC secretion of IL-5 to create eosinophilia." (PMID 37587450, 2023). "With respect to IL-25, mouse models have shown that the administration of IL-25 results in increased AHR, type 2 inflammation, and airway eosinophilia, which can be reversed by the blockade of IL-25." (PMID 33669458, 2021). "IL-25 also induces eosinophil migration in allergic airway models of hypersensitivity, suggesting that ETC-derived IL-25 would contribute to eosinophilia following infection with helminth parasites." (PMID 34578195, 2021). "Eosinophilia is characteristic of EGPA, and some reports suggest that the IL-25 produced by eosinophils promotes innate adaptive immunity by enhancing Th2 cytokine production." (PMID 25174446, 2014). "Similar to Il33−/− mice, Il25−/− mice and Crlf2−/− mice showed attenuated airway eosinophilia after FAP inhalation, suggesting that IL-25 and TSLP, in addition to IL-33, are involved in FAP-induced airway eosinophilia." (PMID 30575775, 2018). "Although both IL-33 and IL-25 were produced by the nasal epithelial cells, we found that the IL-33—but not the IL-25—derived from those cells was crucial for eosinophilia and goblet cell hyperplasia, without affecting Th2 cell development." (PMID 24205109, 2013). "Studies in lung allergy also showed that IL-25 could activate a population of IL-17BR+ NKT cells which resulted in Th2 cell activation and eosinophilia." (PMID 22539101, 2012). "Notably, eosinophilia is enhanced through ILC2 activation by IL-33 and IL-25." (PMID 39962262, 2025). "This could be due to parasite retention in the lung, where reduced eosinophilia and tissue remodelling was observed, and where IL‐25 seemingly does not contribute to immunity, rather than impaired immunity at the intestinal stage." (PMID 40944312, 2025). "Whether IL-25 and IL-33-mediated eosinophilia occurs in other subtypes of CRC inhibiting tumorigenesis remains to be established, however unlike CAC, most studies are concordant with IL-25 and IL-33 promoting tumorigenesis in APC-mutation-mediated CRC." (PMID 36263033, 2022). "In addition, nasal epithelial cell-produced IL-33, rather than IL-25, was important for induction of local inflammation—such as eosinophilia and goblet cell hyperplasia—in HDM-induced AR." (PMID 24205109, 2013). "Treatment of IL5Tg mice with IL-33, but not IL-25 or TSLP, also induced a synergistic increase in bronchoalveolar lavage (BAL) eosinophilia." (PMID 33974563, 2021). "Whereas IL-33, IL-25 and thymic stromal lymphopoietin (TSLP) are involved in induction of FAP-induced ILC-mediated airway eosinophilia, IL-33—rather than IL-25 and/or TSLP—was critical for the eosinophilia in our model." (PMID 30575775, 2018).
psoriasis (39 papers, 2015 to 2026). An autoimmune condition characterized by red, well-delineated plaques with silvery scales that are usually on the extensor surfaces and scalp. "Psoriasis has been found to be associated with higher level of IL-25 in patients compared to normal subjects." (PMID 37005677, 2023). "IL-25 (IL-17E) is significantly upregulated in human psoriatic lesions and is capable of inducing psoriasis-like pathological features in mice, such as acanthosis, parakeratosis, and immune cell infiltration." (PMID 40731810, 2025). "An increase in the IL25 level contributes to the development and increased severity of skin diseases (e.g., dermatitis and psoriasis), which are statistically less common in Yakutia." (PMID 39769502, 2024). "IL-17E (also known as IL-25) produced by Th17 cells induces allergic responses and activates the Th2 pathway; nonetheless, the Th2 psoriasis inflammatory circuit has an inhibitory effect in the Th17 cell-mediated inflammation model." (PMID 38239345, 2023). "The correlation between IL-17 (derived from Th17 cells) and the inflammation present in psoriasis is also seen with another inflammatory mediator, IL-25, a member of the IL-17 cytokine family that is also significantly expressed in psoriasis lesions." (PMID 37997995, 2023). "Subsequently, we will summarize the current knowledge around IL-17A and its five currently known homologues, namely IL-17B, IL-17C, IL-17D, IL-17E (also known as IL-25) and IL-17F, in relation to psoriasis with a focus on the most recent discoveries." (PMID 37283755, 2023). "In this review, we will summarize the current knowledge around IL-17A and its five currently known homologues, namely IL-17B, IL-17C, IL-17D, IL-17E (also known as IL-25) and IL-17F, in relation to skin inflammation in general and psoriasis in particular." (PMID 37283755, 2023). "We also treated HMEC-1 cells with psoriasis-related cytokines such as IL-17A, IL-22, IL-25, IFN-γ, TNF-α, and, VEGF-A, and among them, IFN-γ significantly upregulated the expression and secretion of IGFBP7 in HMEC-1 cells." (PMID 36917196, 2023). "Keratinocytes appear to be the main source of IL-25 in psoriasis, and its expression is tightly regulated by IL-17A." (PMID 34201664, 2021). "Although IL-25 is considered closer to Th2 immunity, it has been found to be strongly expressed in keratinocytes in psoriasis, playing a critical role in its development." (PMID 34201664, 2021). "IL-25 is highly expressed in the skin lesion of patients with psoriasis and in a mouse model of psoriasis." (PMID 34122457, 2021). "As the major IL-17RB-expressing cells in psoriasis, keratinocytes can be activated by IL-25 via activation of STAT3 transcription factor." (PMID 34122457, 2021). "This self-regulatory loop of IL-25 may present a promising therapeutic target for psoriasis, with potentially fewer adverse effects, particularly since its inhibition does not impair IL-17-mediated immune responses against infections." (PMID 40731810, 2025). "IL-17E (also termed IL-25), which is abundant in the lesional skin of patients with psoriasis, was found to be mediated by IL-17 in a murine imiquimod-induced psoriasis model." (PMID 37816755, 2023). "Subsequently, study found that keratin-forming cells from skin in psoriasis patients could express IL-25 and also express IL-25R." (PMID 37005677, 2023). "An intradermal injection of recombinant IL-25 into the ear or dorsal skin of mice was identified to induce psoriasis-like pathology, including epidermal acanthosis and dermal thickening, dermal immune cell infiltration, and pustule formation in the mouse model." (PMID 37005677, 2023). "IL-25 is highly expressed in skin lesions of patients with psoriasis and AD." (PMID 36834723, 2023). "Notably, blockade of IL-17RA using Brodalumab, a co-receptor for IL-17A, IL-17F and IL-25, has shown high efficacy in the treatment of psoriasis." (PMID 34122457, 2021).
psoriasis (continued). "IL-25 is found to promote proliferation of IL-17RB+ keratinocytes and exacerbation of psoriasis." (PMID 34122457, 2021). "Furthermore, brodalumab, which is a human monoclonal antibody human anti-IL17RA, a pan inhibitor of IL-17A, IL-17F, and IL-25 is currently used in the treatment of psoriasis where shows a complete clearance of moderate-to-severe psoriasis." (PMID 33574815, 2020). "In the Il25−/−mouse model of psoriasis, the expression of IL-17 A was reduced, which may be attributed to the reduced recruitment of IL-17 A-producing γδ T cells in psoriasis-like skin inflammation." (PMID 37005677, 2023). "Furthermore, Il17a−/−mice injected with recombinant mouse IL-25 still induced psoriasis." (PMID 37005677, 2023). "Moreover, other results point to the requirement of IL-25 expression in psoriasis." (PMID 34201664, 2021). "Brodalumab, a monoclonal antibody binding to IL-17 receptor A and blocking IL-17A, IL-17C, IL-17F, IL-17A/F, and IL-17E (also known as IL-25), got the FDA approval for adult psoriasis in 2017." (PMID 41481132, 2026). "IL-25 has been reported to promote the proliferation of keratin-forming cells in the skin via the JAK1/2 and STAT3 pathways in a mouse model of psoriasis, inducing large amounts of inflammatory cytokines and chemokines in the skin of the mice." (PMID 37005677, 2023). "Like IL-23, IL-17E (IL-25) is derived from both immune cells and keratinocytes, which was highly expressed in the epidermal layer of lesional skin of psoriatic patients and IMQ-induced psoriasis mouse model." (PMID 35075118, 2022). "Expression of IL-17C, but not IL-25, is increased in psoriatic lesions, which indicates a less important role for IL-25 in psoriasis." (PMID 29104241, 2017). "Consequently, we showed that the skin of IMQ-induced mice mimics the psoriatic characteristics with increased infiltration of inflammatory cells and increased levels of psoriasis-related cytokines and chemokines such as CXCL1, IL-25, IL-17A, IL-6, IL-1β, IL-36, CD4, and IFN-γ." (PMID 34641629, 2021). "The epithelium-derived cytokines, namely TSLP, IL-25 and IL-33 represent a new target for future therapies, especially in terms of itch control and, possibly, side-effects minimization, but not enough studies, especially in psoriasis, have been conducted in this direction." (PMID 34944487, 2021). "A study in psoriasis and control patients, had earlier found highly increased levels of both IL-25 mRNA and protein in keratinocytes of psoriatic lesions, compared to non-lesional or control samples; furthermore, these IL-25+ cells outnumbered IL-17A+ cells in papillary dermis." (PMID 34201664, 2021).
colitis (37 papers, 2012 to 2026). Inflammation of the colon. "In a dextran sulfate sodium (DSS)-induced colitis mouse model, administration of recombinant IL-25 significantly reduced clinical symptoms of colitis, including weight loss and colon ulceration, and prolonged the survival period of the mice." (PMID 40356895, 2025). "Conversely, in a type‐2 colitis model induced by oxazolone, IL‐25 signaling was shown to be pathogenic by enhancing the production of IL‐13, a major epithelium‐toxic cytokine." (PMID 35593111, 2022). "Our current study demonstrated that mice genetically deficient in IL-25 were partially protected from DSS-induced colitis, a model with a Th1/Th17 dominant response at the early acute stage that shifts to a type 2 response in the chronic stage." (PMID 25937893, 2014). "The relative resistance to colitis resulted from IL-25 deficiency was evidenced by significantly decreased disease activity as well as histological activity index, and was associated with reduction of various pro-inflammatory cytokines/mediators in the colon." (PMID 25937893, 2014). "Our present study shows that mice deficient in IL-25 are partially protected from DSS-induced colitis in mice associated with lower expression of IL-33 and other pro-inflammatory cytokines/mediators in the colon." (PMID 25937893, 2014). "To explore the potential mechanisms underlying the relative protection of IL-25−/− mice against DSS-induced colitis, we evaluated the immune response in colonic tissues collected from mice exposed to acute or chronic DSS treatment." (PMID 25937893, 2014). "We investigated the contribution of endogenous IL-25 to DSS-induced colitis using mice deficient in IL-25." (PMID 25937893, 2014). "In the present study, however, mice with a genetic IL-13 deficiency had significantly more severe colitis after exposure to DSS contrary to that observed in IL-25−/− mice, indicating an anti-inflammatory effect of IL-13." (PMID 25937893, 2014). "However, the deficiency in IL-25 was protective against dextran sulfate sodium (DSS)-induced colitis and a defective expression of IL-17B exacerbated the development of acute colitis." (PMID 37005677, 2023). "Interestingly, although IL-17B and IL-17E (IL-25) share a common receptor, IL-17RB, IL-17B, and IL-17E deficiency lead to opposite results in a model of acute colitis induced by dextran sulfate sodium." (PMID 32373132, 2020). "To address whether resistance to DSS-induced colitis conferred by IL-25 deficiency was attributable to a defect in IL-13 expression, we exposed IL-13−/− mice to DSS for seven days." (PMID 25937893, 2014). "In the current study, we replicated previous results that showed up-regulation of IL-33 in DSS-induced colitis and, more importantly, demonstrated that resistance of IL-25−/− mice to DSS-induced colitis was associated with diminished IL-33 expression in the colon." (PMID 25937893, 2014). "Interestingly, IL-25-deficient mice display resistance to DSS-induced colitis while IL-25 upregulates IL-33, IL-6 and TNFα expression in colonic epithelial cells, indicating that IL-25 may contribute to the pathogenesis of IBD." (PMID 34122457, 2021). "IL-25 exerts protective roles in colitis by suppressing intestinal inflammation and maintaining immune homeostasis, primarily through modulating Th2 responses and inhibiting Th1/Th17 pathways." (PMID 41041315, 2025). "In oxazolone-induced UC, blocking IL-25 signaling with IL-25 neutralizing antibodies significantly improves colitis, implicating the role of IL-25 in Th2-driven pathology." (PMID 41041315, 2025). "IL-25 is also proposed as a critical anti-inflammatory cytokine in trinitrobenzene sulfonic acid (TNBS)-induced colitis, where miR-31-mediated targeting of IL-25 suppresses IL-12/23-dependent Th1/Th17 inflammatory responses." (PMID 41041315, 2025). "Epithelial-specific IL-25 deletion reduces IL-1β, IL-6, TNF-α, and CCL2 levels in DSS-treated mice, correlating with decreased colitis-associated tumorigenesis." (PMID 41041315, 2025).
colitis (continued). "In Clostridioides difficile infection (CDI) colitis models, IL-25 expression is suppressed, and IL-25 supplementation restores eosinophil numbers and reduces mucosal injury—despite no changes in bacterial burden or toxin levels." (PMID 40860650, 2025). "Previous study shows that IL17B can compete with IL25 for binding IL17RB to inhibit the pathologic role of IL25 in colitis." (PMID 36814913, 2023). "The protective role of IL17B in colitis is assumed to competitively inhibit IL25-driven colon inflammation." (PMID 36814913, 2023). "DCLK1+ tuft cells which are the main producers of IL25 in the intestine had stem cell properties and played an important role in colitis and CRC initiation." (PMID 35359953, 2022). "We also confirmed that colonic ILC2s obtained from DSS-induced colitis mice showed significantly reduced IL-5 production only when stimulated with IL-25 and IL-33 alone or in combination." (PMID 36268010, 2022). "It was found that IL25 was upregulated in DSS-induced colitis and played a significant role in intestinal parasitic infection and type 2 immunity." (PMID 35359953, 2022). "It is likely that IL25 promotes colitis in an IL33 dependent manner on C57BL/6J, but promotes IL13 in BALB/c, which leads to the differences between the disparate strains." (PMID 35359953, 2022). "IL-25 also shows tumor suppressive properties; blocking IL-25 signaling in a colitis-induced tumor model increases tumor numbers when compared with control mice." (PMID 34581755, 2021). "miR-31 was upregulated in the colon tissues of both UC and CD patients 88; this miRNA is known to target IL-25 to stimulate the Th1/Th17-mediated pro-inflammatory molecular pathway in mouse colitis models." (PMID 34131410, 2021). "As this in turn correlated with limited disease pathology, it was suggested that IL-25 promotes colitis by subsequent activation of ILC2s." (PMID 30999584, 2019). "A study using oxazolone to induce colitis in mice recently demonstrated that expression of IL-13 was enhanced in ILC2s in response to IL-25." (PMID 30999584, 2019). "Other studies have demonstrated that the epithelial-derived cytokine IL-25 mediates the anti-inflammatory protection by H. diminuta in DNBS-induced colitis." (PMID 30670631, 2019). "If IL-25 in CD mice was cleared or the content of IL-25 in the colon was decreased, the treatment effects of miR-31 inhibitors on colitis were significantly decreased." (PMID 30345318, 2018). "In this context, we note that IL-25 inhibits IL-12 and Th-1 cell-driven inflammation in colonic samples from patients and experimental colitis." (PMID 29312281, 2017). "Using a well-established murine model for colitis-induced colon cancer; we aimed to determine the role of IL-25 in this process." (PMID 27165713, 2016). "IL-25 blockade was shown to be protective in a mouse model of colitis resulting in decreased type-2 cytokines, blood eosinophils, and IgE24." (PMID 27165713, 2016). "Several studies also showed that exogenous IL-25 either ameliorates or aggravates colitis in mice depending on the disease model of colitis employed (." (PMID 25937893, 2014). "This is consistent with the observation that protection against DSS colitis in IL-25−/− mice was lost by the third cycle of DSS treatment." (PMID 25937893, 2014). "Together with their ability to produce IL-33 in response to IL-25, intestinal epithelial cells are likely an important player mediating the pro-inflammatory role of IL-25 in DSS-induced colitis." (PMID 25937893, 2014). "The reason for the inconsistency is not known, but a follow-up study from the same group indicated that only high doses (0.8 μg daily) of exogenous IL-25 protected, while low doses (0.2 μg daily) of IL-25 aggravated the DSS-induced colitis." (PMID 25937893, 2014). "In fact, both up-regulation and down-regulation of the IL-25 expression in the colonic mucosa were reported in patients with IBD or experimental murine models of colitis." (PMID 25937893, 2014).